POSTN (periostin)
Diseases named in the same sentence as POSTN in open-access papers (continued):
Sharing a sentence is not in itself a finding about the gene and the disease.
invasive breast carcinoma (4 papers, 2006 to 2024). A carcinoma that infiltrates the breast parenchyma. "Association between periostin expression and clinicopathological parameters in invasive breast carcinomas." (PMID 29161296, 2017). "Stromal and epithelial periostin expression was significantly higher in invasive breast cancer than in normal tissue and DCIS." (PMID 29161296, 2017). "POSTN (Periostin), a mesenchyme-specific gene, has been recurrently identify as highly expressed in invasive breast cancer, in agreement with our results." (PMID 27708222, 2016). "Immunohistochemical staining with anti-periostin antibody was performed in a total of 300 patients (26 patients with normal breast tissues, 76 patients with ductal carcinoma in situ [DCIS], and 198 patients with invasive breast carcinoma [IBC]) using tissue microarray." (PMID 29161296, 2017). "Similarly to POSTN, COMP and IL8 could be clearly detected in the epithelial cells of 21% and 13.9% invasive breast carcinomas, respectively." (PMID 17014703, 2006).
lung squamous cell carcinoma (4 papers, 2017 to 2024). "We also analyzed the TCGA dataset of lung squamous cell carcinoma, which revealed higher levels of periostin expression in tumor tissue compared with paired adjacent normal tissue." (PMID 28977942, 2017).
lupus nephritis (4 papers, 2020 to 2023). Glomerulonephritis in the context of systemic lupus erythematosus. "Lupus nephritis (LN) is the second most common causes of nephritic syndrome in the general population and a gene profiling data analysis identified the periostin expression gene as one of four extracellular protein differentially-expressed genes in this setting." (PMID 36551967, 2022). "Similar findings were described for the urinary fraction of periostin in the setting of lupus nephritis." (PMID 36551967, 2022). "Subsequent studies related to lupus nephritis found that the periostin staining score of lupus nephritis tissue is correlated with the chronic index (CI) of renal pathology, and is positively correlated with blood creatinine and urea nitrogen and negatively correlated with eGFR." (PMID 33241962, 2020). "Periostin staining score of lupus nephritis tissue is correlated with the chronic index (CI) of renal pathology, which is positively correlated with blood creatinine and urea nitrogen and negatively correlated with eGFR, suggesting that Periostin can be used as a marker of renal injury." (PMID 33241962, 2020). "Furthermore, periostin plays a crucial role in the platelet-derived growth factor (PDGF)-induced proliferation of mesangial cells and the accumulation of the extracellular matrix in lupus nephritis." (PMID 35967373, 2022).
nonalcoholic fatty liver disease (4 papers, 2016 to 2020). "Consistently, we and others found that elevated circulating Periostin level was associated with an increased risk of developing nonalcoholic fatty liver disease [18,]." (PMID 31918919, 2020). "Circulating periostin has been suggested as a possible biomarker in non-alcoholic fatty liver disease (NAFLD) in Asian studies." (PMID 33255560, 2020).
oral cancer (4 papers, 2006 to 2021). "In fact, we detected Periostin in condition media of oral cancer cell lines with high expression of Periostin." (PMID 17060937, 2006). "Here, we demonstrated that Periostin overexpression enhanced invasiveness in oral cancer cell lines." (PMID 17060937, 2006). "Here, we confirmed that exogenous Periostin expression strongly enhanced invasive activity in oral cancer cells." (PMID 17060937, 2006). "To confirm whether Periostin can enhance the invasive activity of oral cancer cells, we examined the invasiveness by in vitro invasion assay in Periostin transfectant OSCC cell lines." (PMID 17060937, 2006). "In summary, these findings suggest that Periostin may promote invasion and angiogenesis in OSCC, and that Periostin can be a strong marker for prediction of metastasis in oral cancer patients." (PMID 17060937, 2006). "On literature search for proteomic profiling of POSTN, TNC, CAV1 and FSCN1 in OSCC or oral cancer, we could not find any related studies reported till date." (PMID 33739025, 2021).
oral squamous cell carcinoma (4 papers, 2007 to 2022). "In a study, the correlation between periostin and oral squamous cell carcinoma (OSCC) metastasis and invasion was evaluated by measuring the periostin mRNA level in tumor tissues." (PMID 36224629, 2022).
Osteochondroma (4 papers, 2014 to 2022). A common, benign cartiliginous neoplasm arising from the metaphysis of bone. "There was no specific staining of the chondroid matrix or cartilage cells for periostin in enchondroma, osteochondroma, or low/high-grade conventional chondrosarcoma." (PMID 30202513, 2018). "Periostin was strongly expressed in the perichondrium covering osteochondromas and in areas of endochondral ossification at the base of growing osteochondromas but there was no staining in cells or matrix of the cartilage cap." (PMID 30202513, 2018).
papillary thyroid cancer (4 papers, 2017 to 2024). "In this study, we employed an orthotopic mouse model of papillary thyroid tumor to investigate the function of POSTN in papillary thyroid cancer." (PMID 38773979, 2024). "TIMP1, LOX, CD276, IFNA1, TLR2, and POSTN have different expressions in PTCs, which lead to the various clinical courses of a woman older than 55 years old with papillary thyroid cancer." (PMID 36120433, 2022). "According to the ROC results, TIMP1, LOX, CD276, IFNA1, TLR2, and POSTN were considered to play a more critical role in malignant papillary thyroid cancer or immature cancer of papillary thyroid cancer." (PMID 36120433, 2022). "Previous study demonstrated that POSTN is upregulated in papillary thyroid cancer." (PMID 38773979, 2024). "By analyzing 85 samples from the GSE33630 dataset, we found that POSTN and IL-4 were significantly up-regulated both in papillary thyroid cancer and anaplastic thyroid cancer tissues relative to normal thyroid tissues and POSTN levels were positively correlated with IL-4 in papillary thyroid cancer." (PMID 38773979, 2024). "However, how POSTN regulates papillary thyroid cancer progression remains largely unclear." (PMID 38773979, 2024). "We also found that POSTN was not expressed in normal thyroid epithelial cell line (Nthy-ori-3-1) and papillary thyroid cancer cell lines." (PMID 38773979, 2024). "Nevertheless, the role of POSTN in papillary thyroid cancer has not been fully explored." (PMID 38773979, 2024).
prostate tumors (4 papers, 2011 to 2022). "The increases of periostin total staining intensity were found in the prostate tumors with increased Gleason score in the three TMAs from JHU, the three TMAs from UCLA, and the three TMAs from UCI." (PMID 25781169, 2015). "In the present study, periostin was found to be upregulated and specifically localized to the breast and prostate tumor stroma compared to the normal stroma by immunohistochemistry." (PMID 21611158, 2011). "Prior glycoproteomics analysis of aggressive and non-aggressive CaP tissues showed that periostin was significantly increased in aggressive prostate tumors." (PMID 25781169, 2015). "The periostin total staining was increased in prostate tumor with Gleason score 6 and up compared to paired non-tumorous prostate tissues." (PMID 25781169, 2015). "The expression of periostin was further evaluated in primary radical prostatectomy (RP) prostate tumors and adjacent non-tumorous prostate tissues using immunohistochemistry (IHC)." (PMID 25781169, 2015).
sarcoma (4 papers, 2022 to 2025). A usually aggressive malignant neoplasm of the soft tissue or bone. "Analysis of human sarcoma datasets revealed that high POSTN expression correlates with poor prognosis and elevated expression of ECM-related and myeloid cell-associated genes." (PMID 41448855, 2025). "In this study, we identify periostin (POSTN), a matricellular protein, as a regulator of sarcoma progression and the tumor immune microenvironment." (PMID 41448855, 2025). "Then, we analyzed the expression of biomarkers of osteoblasts (COL1A1, BGLAP and RUNX2), chondrocytes (COL2A1, COMP and SOX9) and sarcoma (POSTN and DCN), adipocyte (LPL and PPARG) and BMSCs." (PMID 39715773, 2024). "Subsequent analysis of gene expression profiles showed that POSTN was highly expressed in 262 cases with sarcoma and expression was closely related to poor prognosis." (PMID 35057799, 2022). "Because the DEGREE algorithm ranked POSTN as the major gene, we used the Kaplan–Meier method to assess the relationship of POSTN expression on the prognosis of 131 patients with sarcoma." (PMID 35057799, 2022).
Arthritis (3 papers, 2013 to 2022). Inflammation of a joint. "Furthermore, tenascin-C expression was increased before and after arthritis onset, whereas periostin expression trended to increase only after arthritis onset in AIA rats ankles." (PMID 34956224, 2021).
Barrett esophagus (3 papers, 2010 to 2016). Esophageal lesion lined with columnar metaplastic epithelium which is flat or villiform. "In a study on Barrett’s esophagus, a 7-fold transcriptional upregulation of POSTN was reported as compared to normal esophageal tissue." (PMID 24281036, 2010).
bronchiolitis (3 papers, 2019 to 2025). Inflammation of the bronchioles characterized by swelling of the bronchioles and mucus accumulation. "In contrast to TSLP, the nasal detection of periostin at admission for bronchiolitis was associated, in our series, with a more favourable respiratory outcome." (PMID 36694181, 2023). "Children hospitalized for bronchiolitis between October/2013 and July/2017, currently aged 4 years, included in a previous study to investigate the nasal airway secretion of TSLP and periostin during bronchiolitis, were included." (PMID 36694181, 2023). "Measurable nasal levels of TSLP were detected at admission for bronchiolitis in 27 (11%) cases and periostin in 156 (63%)." (PMID 36694181, 2023). "Periostin was detected in 156 cases, more often in infants with a maternal history of atopy (p = 0.015) and in those with RSV-bronchiolitis (p = 0.06)." (PMID 36694181, 2023). "There is growing evidence that TSLP and periostin are elicited in the upper airways of infants with RSV and HRV bronchiolitis, and increased TSLP levels are related to more severe disease and intensive care unit (ICU) admission." (PMID 36694181, 2023).
cerebral infarction (3 papers, 2021 to 2024). An ischemic condition of the brain, producing a persistent focal neurological deficit in the area of distribution of the cerebral arteries. "As the pathophysiology, prognosis and clinical features of acute small vessel ischemic strokes are different from other types of cerebral infarcts, anethiology-based intergroup comparison of systemic concentration of periostin would be worthwhile in the future." (PMID 36010292, 2022). "At least in mice with acute MI in vivo, both periostin and α-SMA were upregulated in cardiac fibroblasts by day 2; in mice with cerebral infarction however, periostin levels were transiently suppressed in the ischemic region over 3 h post-insult." (PMID 38652279, 2024).
chronic allograft nephropathy (3 papers, 2012 to 2021). "We also observed an intense predominantly extracellular staining for periostin in the injured fibrotic tubulo-interstitial regions of chronic allograft nephropathy, which further demonstrates overexpression of periostin in human kidney disease." (PMID 22403621, 2012). "Similarly, a negative correlation was reported with urinary periostin in IgAN and chronic allograft nephropathy (CAN) and urinary CK-18 in CKD." (PMID 34768419, 2021).
chronic pancreatitis (3 papers, 2020 to 2023). A chronic inflammatory process causing damage and fibrosis of the pancreatic parenchyma. "As another example, the ECM protein periostin (POSTN), known to promote tumorigenesis, is secreted by activated pancreatic stellate cells and is highly upregulated in the stroma in cases of chronic pancreatitis and PDAC." (PMID 37452870, 2023). "This study also corroborates previous reports of perilobular and interacinar periostin upregulation in chronic pancreatitis." (PMID 32552827, 2020). "Periostin has been reported to increase eosinophil migration and activation, and may be a mechanism that facilitates an increased number of eosinophils in chronic pancreatitis." (PMID 32552827, 2020).
Crohn disease (3 papers, 2021 to 2025). A gastrointestinal disorder characterized by chronic inflammation involving all layers of the intestinal wall, noncaseating granulomas affecting the intestinal wall and regional lymph nodes, and transmural fibrosis. "In a recent study, an inverse association between circulating periostin and disease activity index in pediatric Crohn’s disease has been found, suggesting a more prominent role in repair rather than fuelling inflammatory cascades in this disease." (PMID 34512647, 2021). "Crohn’s disease patients in remission showed significantly higher levels compared to those with active disease, with a linear regression plot demonstrating an inverse association between disease activity scores and periostin levels (r2 = 0.1196, p = 0.003)." (PMID 33737520, 2021). "We found that plasma periostin levels were significantly increased during remission compared to active Crohn’s disease." (PMID 33737520, 2021). "In this study, we observe an inverse association between circulating periostin and disease activity index in Crohn’s disease, suggesting a more prominent role in repair rather than fuelling inflammatory cascades in this immunologically driven disease." (PMID 33737520, 2021).
dermatofibrosarcoma protuberans (3 papers, 2018 to 2024). Dermatofibrosarcoma protuberans (DFSP) is a rare infiltrating soft tissue sarcoma, generally of low grade malignancy, arising from the dermis of the skin and characteristically associated with a specific chromosomal translocation t(17;22). "Periostin (POSTN), for example, is highly expressed in the tumor stroma of myelofibrosis and dermatofibrosarcoma protuberans (DFSP)." (PMID 39003350, 2024).
genitourinary cancers (3 papers, 2016 to 2022). "Upregulation of periostin is associated with adverse clinicopathological factors and poor patient outcomes in genitourinary cancers such as prostate, renal, and penile cancers." (PMID 35850759, 2022). "Among genitourinary cancers, periostin up-regulation is associated with poor pathologic features and poor patient outcome in prostate, renal, and penile disease." (PMID 26981774, 2016).
glaucoma (3 papers, 2020 to 2021). Increased pressure in the eyeball due to obstruction of the outflow of aqueous humor. "Both COL8A2 and POSTN have been reported to be associated with glaucoma." (PMID 34440692, 2021). "Heat shock protein 70, periostin, and irisin levels increase in the aqueoushumor of patients with pseudoexfoliation without glaucoma." (PMID 33084814, 2020). "Finally, the matricellular proteins periostin (PN) and TNC were studied, in a target analysis, in the aqueous humor of NVG patients, obtaining significantly higher levels when comparing glaucoma patients with subjects diagnosed with proliferative diabetic retinopathy." (PMID 34439995, 2021). "In this study, we comparedlevels of aqueous humor HSP-70, periostin, and irisin in patients with PEX andcataract without glaucoma to those in patients with cataract without PEX." (PMID 33084814, 2020). "In conclusion, HSP-70, periostin, and irisin increase in the aqueous humor ofpatients with PEX without glaucoma." (PMID 33084814, 2020). "We aimedto identify molecules that may be associated with the pathogenesis of PEX syndrome.We included only patients without glaucoma in the study, to prevent confoundingeffects of glaucoma and increased intraocular pressure on the aqueous humor HSP-70,periostin, and irisin levels." (PMID 33084814, 2020).
hematoma (3 papers, 2013 to 2024). A hematoma is a collection of blood from a vascular structure into an extravascular space. "POSTN+ IIFCs and immune cells were the main populations present in hematoma and activated periosteum." (PMID 39642053, 2024). "Moreover, serum periostin concentrations resembled hematoma volume and NIHSS score in terms of predictive value assessed by AUCs for 6-month unfavorable outcome." (PMID 36010292, 2022).
Hyperglycemia (3 papers, 2018 to 2023). An increased concentration of glucose in the blood. "Hyperglycemia stimulated the expression of periostin in a TGF-β/Smad-dependent manner." (PMID 37993768, 2023). "Therefore, our results indicate that Periostin is required for GCs-induced hepatosteatosis and hyperglycemia in mice." (PMID 31918919, 2020). "The observation that STZ-treated mice exhibit increased periostin staining in their myocardium compared to control-treated mice in response to HFC diet feeding is consistent with enhanced cardiac remodeling in response to hyperglycemia." (PMID 30356742, 2018).
hypertrophic cardiomyopathy (3 papers, 2012 to 2023). A condition in which the myocardium is hypertrophied without an obvious cause. "The current study aims to investigate the extent of periostin expression in patients with advanced Hypertrophic Cardiomyopathy (HCM) and its correlation with fibrosis and hallmark histopathological features of the disease." (PMID 37939043, 2023). "More recently, murine models of hypertrophic cardiomyopathy showed high levels of periostin expression in the fibrotic areas and genetic ablation of periostin reduced non-myocyte proliferation and fibrosis." (PMID 23700403, 2013). "Accordingly, periostin is induced in models of ischemic, hypertensive and hypertrophic cardiomyopathies, and an AT1 receptor antagonist decreases the cardiac expression of periostin." (PMID 22403621, 2012).
invasive ductal breast carcinoma (3 papers, 2022 to 2024). The most common type of invasive breast carcinoma, accounting for approximately 70% of breast carcinomas. "The results of the present study are in line with our previous observations regarding POSTN expression in cancers cells of invasive ductal carcinoma (IDC) as well as in the stromal compartment (CAFs) of NSCLC." (PMID 35163164, 2022).
ischemia (3 papers, 2022 to 2024). A hypoperfusion of the BLOOD through an organ or tissue caused by a PATHOLOGIC CONSTRICTION or obstruction of its BLOOD VESSELS, or an absence of BLOOD CIRCULATION. "Serum periostin levels were increased at 6 days and beyond at 4 weeks post-ischemia and were positively correlated with severity in terms of infarct volume and neurological deficit, but not with functional outcome in patients with large-artery atherosclerotic stroke." (PMID 36010292, 2022). "Therefore, further studies are warranted to explore the real specificity of periostin in early brain damage due to ischemia." (PMID 36010292, 2022). "Cultured CF expressed notable amounts of alpha-smooth muscle actin (α-SMA) and periostin, indicating a degree of myofibroblast differentiation; periostin but not α-SMA showed a lower expression after simulated ischemia." (PMID 38652279, 2024).
liver cirrhosis (3 papers, 2018 to 2022). "The chi-squared analysis revealed that POSTN overexpression was associated with tumor number, liver cirrhosis, tumor thrombus, and TNM stage." (PMID 33083453, 2020). "Our data indicated that POSTN promoted the expression of matrix proteins such as α-SMA and collagen in hepatic stellate cells, and the clinical correlation analysis revealed that high POSTN was associated with liver cirrhosis." (PMID 33083453, 2020). "Further research revealed that miR-876 and POSTN were inversely correlated in HCC samples and associated with EMT, liver cirrhosis, and tumor invasion." (PMID 33083453, 2020). "As expected, we found that POSTN also affected liver cirrhosis." (PMID 33083453, 2020). "In addition, we found that HCC patients with liver cirrhosis expressed high POSTN." (PMID 33083453, 2020).